MIR6741 (microRNA 6741)
Synonyms: hsa-mir-6741
Gene: MicroRNA gene on chromosome 1 (225,922,080 to 225,922,142, reverse strand). Ensembl gene ENSG00000284519.
Homologues: Orthologues: chimpanzee MIR6741 (100% identical).